CNTN1 (contactin 1)
Diseases named in the same sentence as CNTN1 in open-access papers (continued):
Sharing a sentence is not in itself a finding about the gene and the disease.
COVID-19 (3 papers, 2022 to 2026). A disease caused by infection with severe acute respiratory syndrome coronavirus 2. "Notably, whereas IL12RB1, NRP1 and NRP2 were only moderately increased as a function of viral load, CNTN1 expression was significantly correlated with viral load in these COVID-19 patients, an association that was more prominent in older patients." (PMID 35931765, 2022). "Moreover, we find that the novel SARS CoV-2 spike interactor CNTN1 is significantly upregulated in two large cohorts of COVID-19 patients." (PMID 35931765, 2022). "Although the current study does not address the functional role of this interaction during real SARS CoV-2 infection, the marked increase of CNTN1 in two independent COVID-19 patient cohorts is thought-provoking and strongly suggests a role for this host factor in vivo." (PMID 35931765, 2022). "Our findings that the nervous cell-associated factor CNTN1 acts as a SARS CoV-2-specific target suggest a possible route by which the virus may interact with cells in the nervous system, which might contribute to the neurological symptoms observed in a high percentage of COVID-19 patients." (PMID 35931765, 2022).
depression (3 papers, 2023 to 2025). "Furthermore, the researchers identified several genes associated with depression, such as Cntn1, TREM2, and P2X7, using SNP (single nucleotide polymorphism) and GWAS association analysis." (PMID 38607738, 2024).
gastric tumor (3 papers, 2013 to 2021). "Both VEGF-C and CNTN-1 were observed almost exclusively in the cytoplasms of gastric tumor cells." (PMID 23606831, 2013). "CNTN-1 mRNA was found to be upregulated in gastric tumors compared to noncancerous gastric samples, and this upregulation was linked to tumor size, TNM stages, metastases, and invasion." (PMID 34659414, 2021).
lupus nephritis (3 papers, 2023 to 2025). Glomerulonephritis in the context of systemic lupus erythematosus. "In individuals with anti-PLA2R1-associated MN or membrane lupus nephritis, or in a healthy control group, glomerular contactin 1 was lacking." (PMID 40502862, 2025).
multiple sclerosis (3 papers, 2018 to 2022). A progressive autoimmune disorder affecting the central nervous system resulting in demyelination. "CASPR1 and CNTN1 are frequent auto‐antigens in auto‐immune diseases including multiple sclerosis." (PMID 30266776, 2018). "Also in the PLP mouse model of multiple sclerosis/optic neuritis, we observed a decrease in CASPR1 and CNTN1 in retinal synapses (Fig 7A1–3 and B1–3; Appendix Fig S13A1–3 and B1–3)." (PMID 30266776, 2018).
acute inflammatory neuropathies (2 papers, 2016 to 2026). "Patients with known AN (23 anti-neurofascin, 13 anti-contactin-1, and 8 anti-Caspr-1), 64 patients with seronegative (sub) acute inflammatory neuropathies, and 30 healthy controls served for validation, including quality analysis versus standard ELISA." (PMID 41906364, 2026).
Alzheimer disease (2 papers, 2019 to 2020). A progressive, neurodegenerative disease characterized by loss of function and death of nerve cells in several areas of the brain leading to loss of cognitive function such as memory and language. "We were also able to identify proteins exclusively observed in Alzheimer’s disease (i.e., RNF213) or only detected in samples not affected by the disease (i.e., CNTN1) after the enrichment process." (PMID 31253170, 2019).
autism (2 papers, 2010 to 2018). Persistent deficits in social interaction and communication and interaction as well as a markedly restricted repertoire of activity and interest as well as repetitive patterns of behavior. "The six candidate genes sequenced, CNTN1, FOXJ2, GRIN2B, NAB2, NELL2 and SRGAP1, were selected based on their putative functions, and their relationships to genes potentially involved in the pathology of language impairments, auditory processing deficits, autism and dyslexia." (PMID 20345892, 2010).
autoimmune disease (2 papers, 2022 to 2025). A disorder resulting from loss of function or tissue destruction of an organ or multiple organs, arising from humoral or cellular immune responses of the individual to their own tissue constituents. "Anti-CNTN1 AN can be regarded as a thymoma-related autoimmune disease." (PMID 40995362, 2025).
Cachexia (2 papers, 2019 to 2020). Severe weight loss, wasting of muscle, loss of appetite, and general debility related to a chronic disease. "We next sought to prevent post-natal lethality in Cntn1-deficient animals through selective blockade or depletion of lymphocyte populations or effector proteins that may mediate inflammation-induced cachexia." (PMID 32676079, 2020). "Based on the fact that circulating levels of tumor-derived factors were correlated with cachexia development and predicted outcome in cancer, we also investigated the predictive potential of seven transcripts (NCAM1, CNTN1, SCG2, CADM1, IL-8, NPTX1, and APOD)." (PMID 31455042, 2019).
demyelinating peripheral neuropathy (2 papers, 2021 to 2025). "Through a literature survey of demyelinating peripheral neuropathy and thymoma, we summarized the clinical features and involvement of CNTN1-IgG." (PMID 40995362, 2025). "Finally, CNTN1-IgG was measured in a part of previous reports describing demyelinating peripheral neuropathy with thymoma." (PMID 40995362, 2025).
encephalitis (2 papers, 2016 to 2021). An acute inflammatory process affecting the brain parenchyma. "Anti-neuronal IgG4-AID include MuSK myasthenia gravis, LGI1- and Caspr2-encephalitis and autoimmune nodo-/paranodopathies (CNTN1/Caspr1 or NF155 antibodies)." (PMID 35095860, 2021).
lymph node metastasis (2 papers, 2012 to 2013). "Our study demonstrates that CNTN1 protein level was markedly associated with lymph node metastasis of patients with OSCC (P=0.006)." (PMID 22580838, 2012). "A significantly high expression level of CNTN1 was found to be markedly association with patients who had regional lymph node metastasis." (PMID 22580838, 2012). "Patients with higher levels of both VEGF-C and CNTN-1 were more likely than those with low or intermediate levels of these proteins to have more advanced stage, more severe lymph node metastasis, lymphatic invasion, and serosa invasion." (PMID 23606831, 2013). "As well known, it had been demonstrated that CNTN-1 might be an adjusting factor in downstream of VEGF-C/VEGFR-3 axis to promote lymph node metastasis." (PMID 23606831, 2013). "Patients with lymphatic invasion, lymph node metastasis, and later TNM staging showed higher expression level of CNTN-1." (PMID 23606831, 2013). "After comparing the differences in clinicopathological outcomes and prognosis between these two groups, the patients with the high expressions of both VEGF-C and CNTN-1 possessed later TNM stage, easier to result in serosa infiltration, lymphatic vessel invasion, and lymph node metastasis." (PMID 23606831, 2013). "Expression of VEGF-C, VEGFR-3, and CNTN-1 was all significantly correlated with TNM stage, lymphatic invasion, and lymph node metastasis, but not with age, gender, tumor size, tumor location, Lauren's classification, vascular invasion, or serosa invasion, respectively." (PMID 23606831, 2013).
neuropathic pain (2 papers, 2019 to 2022). Chronic pain caused by damage to nerve fibers. "Synaptic proteins such as gelsolin, apolipoprotein C1, apolipoprotein E, contactin-1, and neural cell adhesion molecule L1-like protein were altered in cerebrospinal fluid of neuropathic pain patients and contributed to pain treatment." (PMID 36545122, 2022). "Regarding the other candidate proteins identified in this study, Contactin-1 (CNTN1) has been shown to be significantly upregulated after electric stimulation of the spinal cord in neuropathic pain patients." (PMID 30770760, 2019).
non-small cell lung carcinoma (2 papers, 2020). A group of at least three distinct histological types of lung cancer, including non-small cell squamous cell carcinoma, adenocarcinoma, and large cell carcinoma. "Of note, overexpression of interleukin (IL)-8 and CNTN1 is correlated with cachexia in non-small cell lung cancer, indicating a potential link between CNTN1 and immune response in cancers." (PMID 33194679, 2020).
Obesity (2 papers, 2023 to 2024). Accumulation of substantial excess body fat. "Although contactin 1 (CNTN1) is also associated with obesity and adiposity, it regulates the bacterial metabolism of tryptophan (Trp) and thus appetite." (PMID 39408963, 2024). "All except CNTN1 were positively associated with obesity and adiposity." (PMID 39408963, 2024). "The authors identified four biomarkers (leptin, plasminogen activator inhibitor 1 (PAI1), alpha-1 acid glycoprotein 1 (AGP1), and CNTN1) for obesity and adiposity." (PMID 39408963, 2024). "Our analyses highlighted several candidate genes, such as CNTN1—which has been linked to weight loss in mice and is potentially influential for AGE100—and MC4R, which is associated with obesity and appetite and may impact both traits." (PMID 37372438, 2023).
Sensorimotor neuropathy (2 papers, 2015 to 2021). "Recent studies have described a uniform phenotype of patients with anti-neurofascin and anti-contactin-1 auto-antibodies with acute GBS-like onset of sensorimotor neuropathy following chronic course of disease and severe tremor in patients with auto-antibodies against neurofascin-155." (PMID 26218529, 2015).
Sjögren's syndrome (2 papers, 2018 to 2025). "Therefore, we consider anti-CNTN1 antibodies but not Sjögren's syndrome contributory to the present illness of our patient." (PMID 30538665, 2018).
allergic asthma (1 paper, 2022). A asthma with a basis in a pathological type I hypersensitivity reaction. "Recently, a study showed that in epithelial exosomes, contactin-1 (CNTN1) is involved in the activation and recruitment of monocyte-derived dendritic cells and T-cell responses in allergic asthma." (PMID 35062793, 2022).
aortic stenosis (1 paper, 2022). Aortic valve stenosis is a aortic valve disease caused by the incomplete opening of the aortic valve. "The role of CNTN1 in aortic stenosis has not been clarified, which needs further exploration." (PMID 35722091, 2022).
Arthritis (1 paper, 2019). Inflammation of a joint. "Taken together, we found that several proteins with inflammatory function were decreased in arthritis CSF after infliximab treatment, including proteins with additional neuro-immunomodulatory function such as FGG, CNTN1 and CADM3." (PMID 30770760, 2019). "Taken together, we demonstrate that both CNTN1 and CADM3 may be involved in intrathecal processes regulating pain also in arthritis patients." (PMID 30770760, 2019).
asthma (1 paper, 2022). "These dendritic cells secrete IL-4, IL-5, IL-6, IL-13, and IL-17A to drive an enhanced inflammatory response in the airways, suggesting that CNTN1 may act as an inflammatory mediator in the pathology of asthma." (PMID 35492721, 2022). "Recent exosome research has identified a link between CNTN1 and asthma." (PMID 35492721, 2022). "CNTN1 was found to induce Notch2 signaling in asthma to activate Th17 and Th2 cells." (PMID 35492721, 2022).
attention deficit-hyperactivity disorder (1 paper, 2019). A disorder characterized by a marked pattern of inattention and/or hyperactivity-impulsivity that is inconsistent with developmental level and clearly interferes with functioning in at least two settings (e.g. at home and at school). "This cross-sectional study investigates whether BDNF and CNTN1 affect susceptibility to attention deficit/hyperactivity disorder (ADHD)." (PMID 31480710, 2019).
cerebellar pilocytic astrocytoma (1 paper, 2015). A WHO Grade 1 astrocytoma which arises in the cerebellum. "This is the first report where CNTN1 and CNTN3 gene expression were shown to be connected with cerebellar pilocytic astrocytomas biology." (PMID 26497896, 2015).
cerebellar tumors (1 paper, 2015). "Contactin family genes (CNTN1, CNTN3), which function as cell adhesion molecules with an essential role in later stages of cerebellar morphogenesis and differentiation, were also significantly overrepresentated in our cohort of cerebellar tumors." (PMID 26497896, 2015).
cervical cancer (1 paper, 2013). A primary or metastatic malignant neoplasm involving the cervix. "To determine if CNTN-1 regulates E-cadherin and AKT in other cancer cell lines, we examined a number of breast, kidney, lung and cervical cancers for CNTN-1 and E-cadherin expression." (PMID 23724143, 2013).
cognitive deficits (1 paper, 2023). "It would therefore be valuable to understand the precise mechanisms underlying the cognitive impairment induced by CNTN1 overexpression." (PMID 37196127, 2023). "In this study, the role of CNTN1 in cognitive deficits was demonstrated by the finding that hippocampal CNTN1 overexpression caused cognitive impairment in mice, as detected by a series of behavioral assays, including the NORT, NPRT and SRT." (PMID 37196127, 2023). "Taken together, our results identified Cntn1 as a susceptibility factor involved in regulating cognitive deficits via functional actions in the hippocampus." (PMID 37196127, 2023). "Additionally, hippocampal CNTN1 overexpression appeared to cause cognitive deficits in mice, which coincided with the activation of microglia and astrocytes, leading to abnormal EAAT1/ EAAT2 expression with the blockade of synaptic LTP in the hippocampus, which could be prevented by minocycline." (PMID 37196127, 2023). "Considering that CNTN1 expression was markedly increased in postmortem AD brains, we evaluated whether hippocampal CNTN1 overexpression led to development of cognitive deficits in mice." (PMID 37196127, 2023). "In this way, we found that mice with hippocampal CNTN1 overexpression exhibited cognitive deficits." (PMID 37196127, 2023). "Taken together, these results preliminarily supported the notion that increased CNTN1 expression may be a cellular basis for cognitive deficits in mice." (PMID 37196127, 2023). "The possibility of neuroinflammation related negative effects of CNTN1 should be considered, as major efforts have focused on developing CNTN1-based therapeutic targets to mitigate neuroinflammation-associated cognitive deficits." (PMID 37196127, 2023). "Therefore, the inflammation-related cellular mechanisms through which hippocampal CNTN1 overexpression resulted in cognitive deficits were assessed." (PMID 37196127, 2023). "However, the mechanisms and functional roles of CNTN1 as a putative susceptibility factor in neuroinflammation- related cognitive disorders have not yet been characterized." (PMID 37196127, 2023). "Moreover, we sought to identify the mechanisms by which CNTN1 overexpression in the hippocampus could lead to these cognitive impairments in mice." (PMID 37196127, 2023). "In addition, these cognitive deficit-related phenotypes could be pharmacologically reversed by minocycline, which suggested that CNTN1 might be a novel target for therapy of inflammation associated cognitive deficits." (PMID 37196127, 2023). "However, whether CNTN1 plays a role in inflammation-related cognitive deficits and how this process is triggered and orchestrated remain to be fully elucidated." (PMID 37196127, 2023).
dementia with (1 paper, 2021). "rs1442190 is an intronic variant within CNTN1, a known risk gene for dementia with Lewy bodies that encodes a cell adhesion protein, which is important for axon connections and nervous system development." (PMID 35047012, 2021).
dementia with Lewy bodies (1 paper, 2020). "We aimed to investigate whether levels of synaptic proteins contactin-1 and contactin-2 in cerebrospinal fluid (CSF) of PD patients are reduced compared to dementia with Lewy bodies (DLB) patients and controls and to evaluate their relationship with α-synuclein aggregation." (PMID 32806791, 2020). "Previous CSF proteomics-based studies showed lower levels of contactin-1 in PD compared to controls and dementia with Lewy bodies (DLB)." (PMID 32806791, 2020).
embryonal carcinoma (1 paper, 2009). A non-seminomatous malignant germ cell tumor characterized by the presence of large germ cells with abundant cytoplasm resembling epithelial cells, geographic necrosis, high mitotic activity, and pseudoglandular and pseudopapillary structures formation. "We recently developed a co-culture system in which NP stromal cells were shown to induce differentiation of an embryonal carcinoma stem-cell line into a cell type with stromal cell gene expression, including the up-regulation of CNTN1, as well as that of epithelial markers." (PMID 19737398, 2009).
Escobar syndrome (1 paper, 2021). "Escobar syndrome can also be caused by pathogenic variants in CNTN1 (contactin 1) and DOCK7 (dedicator of cytokinesis 7)." (PMID 34440395, 2021).
Failure to thrive (1 paper, 2011). Failure to thrive (FTT) refers to a child whose physical growth is substantially below the norm. "The overt phenotype is very similar to the knockout of Cntn1, with affected animals having reduced body weight, a failure to thrive, locomotor abnormalities, and a lifespan of 2–3 weeks." (PMID 22242131, 2011).
Focal cortical dysplasia (1 paper, 2018). A type of malformation of cortical development that primarily affects areas of neocortex. "Recently, we also found somatic mutations in CNTN1 in the brain lesion of patients with focal cortical dysplasia (FCD)." (PMID 30515076, 2018).
glaucoma (1 paper, 2013). Increased pressure in the eyeball due to obstruction of the outflow of aqueous humor. "For example, Aqp4, astrotactin 1 (Astn1), contactin 1 (Cntn1), and gap junction protein alpha 1 (Gja1) were down-regulated after optic nerve crush, but were up-regulated in glaucoma." (PMID 23826199, 2013).
granulocytosis (1 paper, 2020). "Furthermore, measurements of white blood cells in Cntn1-deficient indicated lymphopenia and granulocytosis." (PMID 32676079, 2020).
immune deficiency (1 paper, 2020). "The identified roles of Contactin-1 in the temporal regulation of gut activity and subsequent immune deficiency at approximately 2–3 weeks post birth provide novel aspects of Contactin-1 function." (PMID 32676079, 2020). "Adequate dietary supplementation should correct HPA imbalances and glucocorticoid signaling, and subsequent immune deficiencies in Cntn1-null animals." (PMID 32676079, 2020).
Infertility (1 paper, 2024). "Moreover, genetic ablation of Cntn1 in a zebrafish model results in infertility, reduced animal size, ataxic swimming behavior, and a curved spine, with hypomyelinated neurons compared to wild-type." (PMID 39254732, 2024).
leukemia (1 paper, 2019). A malignant (clonal) hematologic disorder, involving hematopoietic stem cells and characterized by the presence of primitive or atypical myeloid or lymphoid cells in the bone marrow and the blood. "WES identified all 14 known Notch1 mutations, and also uncovered somatic mutations in the Notch pathway genes Notch4 and Cntn1 in two additional leukemias." (PMID 31199785, 2019).
liver disease (1 paper, 2020). "In the blood of Cntn1-deficient animals we observed elevated liver enzymes, bilirubin, urea, and anisocytosis consistent with nutrient deprivation and liver disease." (PMID 32676079, 2020).
malnutrition (1 paper, 2020). Inadequate nutrition resulting from poor diet, malabsorption, or abnormal nutrient distribution. "Together, these data indicate that Contactin-1 is required for optimal maintenance of neuromuscular and immune homeostasis within the intestinal mucosa and loss-of function leads to malnutrition and subsequent organ dysfunction." (PMID 32676079, 2020). "The hematologic changes in Cntn1−/− animals indicated that wasting was likely due to malnutrition." (PMID 32676079, 2020).
metastatic tumors (1 paper, 2021). "DIRAS1, FBXL16, TP53I11, TFF2, and ZNF467 were upregulated in both metastatic tumors and GHSROS-overexpressing PC3 and LNCaP cells, while AASS, CHRDL1, CNTN1, IFI16, and MUM1L1 were downregulated." (PMID 33585078, 2021).